DMD (dystrophin)
Diseases named in the same sentence as DMD in open-access papers (continued):
Sharing a sentence is not in itself a finding about the gene and the disease.
heart failure (continued). "Two brothers with a deletion of DMD exon 3, showed early onset dystrophy and loss of ambulation, but stabilised in early adulthood and did not have respiratory or cardiac insufficiency." (PMID 26745801, 2016). "In addition, females carrying either the DMD or BMD dystrophin mutation develop heart failure, even in the absence of any skeletal muscle defects." (PMID 35887128, 2022). "Consequently, failure of dystrophin restoration in cardiac tissue, in the presence of rescued protein expression in skeletal muscles, may exacerbate any subclinical heart failure due to increased voluntary muscle activity." (PMID 34832896, 2021). "In the present study, we explored the hypothesis that empagliflozin (EMPA), an inhibitor of sodium/glucose cotransporter 2 in clinical use to treat type II diabetes and nondiabetic heart failure, rescues peak INa loss in dystrophin-deficient ventricular cardiomyocytes." (PMID 38099845, 2024). "Thus, the animals that early lose dystrophin might be those that could progress to heart failure." (PMID 29267303, 2017). "Currently, routine use of preventive treatment with any heart failure medication does not seem appropriate for genetic carriers of DCM-causing variants, with the exception of children with DMD." (PMID 40902100, 2025). "The authors concluded that both dystrophin-negative and dystrophin-positive cardiomyocytes can be damaged during the progression of heart failure." (PMID 39075955, 2024). "Moreover, the ability to perform sequential biopsies allowed us to monitor the progress of heart failure and to correlate the extent of remodeling and its reversal with ANP, ET-1, BAR, and dystrophin levels." (PMID 22347659, 2011). "In affected individuals, the absent or diminished dystrophin leads to progressive skeletal muscle and heart failure." (PMID 20492678, 2010). "Interestingly, we found that activation of dystrophin with dCas9-SAM system restored the membrane distribution of Nav1.5 in cardiomyocytes of lncDach1-TG mice, which implies its potential in counteracting sodium channel remodeling of patients with heart failure." (PMID 39773412, 2025). "Our results suggest that cardiomyocytes can compensate for the lack of dystrophin in the healthy heart (10 kPa), but not the stiff, fibrotic heart (35 kPa), which could explain why DMD patients become increasingly susceptible to arrhythmia and heart failure as they age." (PMID 34019816, 2021).
Cognitive impairment (44 papers, 2008 to 2026). Abnormal cognition is characterized by deficits in thinking, reasoning, or remembering. "We explored potential associations between specific mutation locations and intellectual impairment in our DMD cohort." (PMID 40822690, 2025). "Several studies pointed out that mutations in the second part of the dystrophin gene are associated with cognitive impairment and neuropsychiatric comorbidities as they affect more dystrophin gene products." (PMID 41595432, 2025). "As observed in several studies, mutations in the dystrophin gene, particularly in the distal portion, are often associated with specific cognitive deficits or neurodevelopmental disorders." (PMID 40722287, 2025). "Several authors showed a close association between the increased risk of cognitive impairment and deletions in the distal portion of the DMD gene (ranging from exon 45 to exon 60), specifically those involving the Dp140 isoform." (PMID 40722287, 2025). "The location of the mutation determines the number of dystrophin isoforms affected, and the absence thereof leads to behavioral and cognitive impairments." (PMID 39885828, 2025). "Previous research has shown an association between the location of the dystrophin gene mutation, affecting specific dystrophin isoforms in the brain (i.e., Dp140 and Dp71), and cognitive impairments." (PMID 36421868, 2022). "Further, there are over 7000 mutations in the dystrophin gene known to cause DMD, which combined with the several isoforms of dystrophin found in the brain can also contribute to the varying degree of cognitive impairment in boys with DMD." (PMID 34668666, 2022). "Correlation of Full-Scale Intelligence Quotients (FSIQ) with the location of the DMD gene mutation suggests that the risk of cognitive deficits increases with cumulative loss of dystrophin isoforms." (PMID 35019137, 2022). "We noticed that 55.3% of our DMD group, had distal mutations abolishing the production of Dp140 and it is suggested that these males have more severe cognitive impairments." (PMID 36215287, 2022). "Deletion of exon 52 impedes expression of several brain dystrophins (Dp427, Dp260 and Dp140), thus providing a key model for studying the cognitive impairment associated with DMD and testing rescuing strategies." (PMID 34546327, 2021). "Distal DMD mutations determining the level of shorter dystrophin isoforms, such as Dp140 and Dp71 predominantly expressed in the brain, are associated with cognitive impairment in DMD." (PMID 34091693, 2021). "The DMD gene variant location and its association with variable degrees of cognitive impairment necessitate identification of a common denominator." (PMID 32686699, 2020). "Distal DMD mutations affecting the expression of these shorter variants are linked to cognitive impairment." (PMID 31836945, 2020). "The risk of cognitive impairment in DMD has been associated with the location of mutations within the DMD gene resulting in the absence of specific dystrophin isoforms." (PMID 28974727, 2017). "Several studies have linked the loss of dystrophin expression to cognitive impairments in DMD, with a higher propensity for these impairments being observed in mutations that result in the loss of multiple isoforms." (PMID 28806929, 2017). "Risk of cognitive deficits among DMD patients is thought to be the result of the cumulative loss of dystrophin isoforms in the central nervous system during development." (PMID 23092449, 2012). "Evidence of a link between mutation location within DMD and cognitive deficit was based initially on the observation that deletions of exon 52 were associated with cognitive impairment." (PMID 20098710, 2010). "The correlation of FSIQ results with the location of the DMD mutation is highly suggestive that the risk of cognitive deficit is a result of the cumulative loss of CNS expressed dystrophin isoforms." (PMID 20098710, 2010).
Cognitive impairment (continued). "The novel features of this study are that we confirm that the site of the mutation in the DMD gene is an important determinant of the risk of cognitive deficit." (PMID 20098710, 2010). "In addition to progressive skeletal muscle dysfunction, this multisystemic disorder can also result in cognitive deficits and behavioural changes that are likely to be consequences of dystrophin loss from central neurons and astrocytes." (PMID 39792584, 2025). "Our studies suggest that dystrophin deficiency causes a progressive cognitive impairment in mice (compared to ageing control mice), becoming evident at late disease stages, and may explain why progressive CNS symptoms are not obvious in DMD patients." (PMID 32360405, 2020). "Mutations in the first exons that selectively affect expression of Dp427 lead to moderate cognitive deficits, whereas in about one-third of patients downstream mutations inducing a cumulative loss of the shorter dystrophin products are responsible for moderate to severe intellectual disability." (PMID 29895670, 2018). "The site of a DMD mutation was found to be clearly related to the extent of cognitive deficit." (PMID 20098710, 2010). "This could lead to an imbalance in the exquisite choreography of cellular network activity that underlies salient aspects of hippocampal function such as learning and memory, thereby contributing to the cognitive impairment associated with dystrophin-mutations leading to DMD." (PMID 25260053, 2014). "Recently, interventional studies in mdx mouse models, such as antisense oligonucleotide therapy, have shown restoration of dystrophin in the mouse brain and partial improvement of cognitive impairment." (PMID 40722287, 2025). "In human DMD, increased prevalence of cognitive deficits implicates dystrophin in physiological processes underpinning learning and other behaviours." (PMID 39792584, 2025). "Then, the differences between each couple of subgroups were tested to explore the role of the cognitive deficit and the expression of the Dp140 dystrophin isoform." (PMID 39834775, 2024). "Development of therapeutic strategies to correct the neurobehavioural and cognitive deficits associated with DMD will require a detailed understanding of the precise functions and regional expression patterns of dystrophin isoforms within the brain." (PMID 35019137, 2022). "It is now clear that the frequency and severity of CNS involvement increase with the accumulated loss of distal dystrophin gene products, with DMD mutations after exon 63 (and therefore Dp71 loss) associated with the most severe intellectual impairment." (PMID 31836945, 2020). "An association between the loss of the either Dp427 and/or Dp140 dystrophin protein isoform in DMD subjects and cognitive impairment has been suggested." (PMID 31434868, 2019). "When the main components of the DGC, Dystrophin (Dys) and Dystroglycan (Dg) are affected cognitive impairment and mental retardation in addition to muscle degeneration can occur." (PMID 21943192, 2011). "A relationship between the intellectual impairment and altered expression of the C-terminal brain-expressed dystrophin isoforms was suggested by several case reports." (PMID 20098710, 2010). "Cognitive impairment in some DMD patients has been associated with mutations affecting the distal Dp140 and Dp71 dystrophin isoforms." (PMID 19040728, 2008). "Basic research studies into the pathogenesis of DMD have added to the understanding of the relationship between dystrophin structure and function, and provided some indication of dystrophin isoforms connected with muscle involvement, cognitive impairment, or cardiac disease." (PMID 38596212, 2024). "The same group later demonstrated amongst a larger cohort without DMD deletions or duplications who have severe intellectual impairment that all patients with point mutations resulting in the termination of Dp71 expression were the most severely affected." (PMID 31836945, 2020).
Cognitive impairment (continued). "The absence of functional dystrophin in these brain regions is believed to underlie the cognitive deficits that are present in a subset of individuals with DMD." (PMID 31543764, 2019). "Furthermore, cognitive impairment is generally considered to start in development, with full-length dystrophin having the highest expression in humans at 2 years and being nonprogressive; however, its evolution from the perinatal stage through adolescence to adulthood has not been studied in detail." (PMID 40114059, 2025). "By comparing these models, we can gain important insights into the molecular mechanisms disrupted by each dystrophin isoform expressed in the nervous system, highlighting their contribution to neurologic disorders in DMD and identifying mutation-specific therapeutic strategies for cognitive defects." (PMID 40490752, 2025). "Dp140, Dp71, and Dp40 are also expressed in brain tissue, with cognitive impairment most prominent in patients with mutations in distal region of the DMD gene, which eliminates the expression of full-length dystrophin and one or more shorter dystrophin isoforms." (PMID 32360405, 2020). "Absence of dystrophin or deletion of base pairs in the dystrophin gene is a cause of Duchenne and Becker muscular dystrophy, which are allelic X-linked disorders with a progressive muscle weakness, a static cognitive impairment, autism and problems of behavior and attention." (PMID 31178701, 2019). "Despite rough correlation of cognitive impairment with the mutated region in the dystrophin gene, and of low BMI with better motor outcome, neither genotyping nor nutritional status served to identify DMD subsets, whereas age and type of symptoms at onset, muscle strength at 8 yrs, and IQ, did." (PMID 19194511, 2009). "Notably (unlike muscle) these cognitive deficits do not appear to increase in severity with time, implying either passive, ongoing modulatory involvement of dystrophin, or a stage-sensitive developmental contribution." (PMID 32724863, 2020).
Duchenne and Becker muscular dystrophies (44 papers, 2007 to 2025). "Dystrophin (DMD) gene mutations are associated with skeletal muscle diseases such as Duchenne and Becker Muscular Dystrophy (BMD) and X-linked dilated cardiomyopathy (XL-DCM)." (PMID 38474032, 2024). "Mutations in the dystrophin gene cause Duchenne and Becker muscular dystrophy in humans, mice, dogs, and cats." (PMID 37626825, 2023). "Duchenne and Becker muscular dystrophies (DMD/BMD) are caused by complex mutations in the dystrophin gene (DMD)." (PMID 38047063, 2023). "Duchenne and Becker muscular dystrophies are X-linked recessive NMDs that cause progressive weakness due to mutations in the gene that encodes for dystrophin, a support protein necessary for muscle integrity." (PMID 35207206, 2022). "Duchenne/Becker muscular dystrophy (DMD/BMD) is an X-linked neuromuscular disease due to pathogenic sequence variations in the dystrophin (DMD) gene, one of the largest human genes." (PMID 34679607, 2021). "The mutations in the DMD gene encode the dystrophin protein, causing Duchenne and Becker muscular dystrophies." (PMID 30820831, 2019). "The Duchenne and Becker muscular dystrophies are caused by mutation of dystrophin gene and primarily affect skeletal and cardiac muscles." (PMID 26681949, 2016). "It is interesting to compare the K18N mutation with other dystrophin mutations that trigger Duchenne/Becker muscular dystrophy (DMD/BMD)." (PMID 25340340, 2014). "Dystrophin is associated with Duchenne and Becker muscular dystrophies (DMD), where it is implicated in signaling events and synaptic transmission." (PMID 24473445, 2014). "Genomic rearrangements such as intragenic deletions and duplications are the most prevalent type of mutations in the dystrophin gene resulting in Duchenne and Becker muscular dystrophy (D/BMD)." (PMID 25614876, 2014). "In contrast to Duchenne and Becker muscular dystrophy, caused by a mutation of the muscle-stabilizing protein dystrophin, EDMD is associated with an aberration of the inner nuclear membrane proteins emerin or lamin A/C." (PMID 22973525, 2012). "Duchenne and Becker Muscular dystrophies (DMD/BMD) are allelic disorders caused by mutations in the dystrophin gene, which encodes a sarcolemmal protein responsible for muscle integrity." (PMID 21396098, 2011). "In humans, Duchenne and Becker muscular dystrophies arise from mutations in a single gene encoding the large membrane-associated protein, dystrophin; these diseases are characterized by severe muscle weakening and degeneration." (PMID 17848203, 2007). "It is well-known that DMD gene mutation can cause Duchenne and Becker muscular dystrophy." (PMID 37694778, 2024). "Loss of dystrophin and the subsequent disruption of the dystrophin complex from the sarcolemma ultimately lead to muscle degeneration in patients with X-linked, Duchenne and Becker muscular dystrophy, X-linked conditions caused by mutations in the dystrophin gene." (PMID 25405382, 2015). "Mutations in the dystrophin (DMD) gene cause Duchenne or Becker muscular dystrophy (DMD/BMD)." (PMID 21151598, 2010). "Duchenne and Becker muscular dystrophies (DMD/BMD) result in progressive weakness of skeletal and cardiac muscles due to the deficiency of functional dystrophin." (PMID 31817415, 2019). "A broad mutational spectrum in the dystrophin (DMD) gene, from large deletions/duplications to point mutations, causes Duchenne/Becker muscular dystrophy (D/BMD)." (PMID 28972564, 2017). "Duchenne and Becker muscular dystrophy severity depends upon the nature and location of the DMD gene lesion and generally correlates with the dystrophin open reading frame." (PMID 26745801, 2016). "With respect to DMD alterations, it is well-established that dystrophin deficiency causes Duchenne and Becker muscular dystrophies; however, its role in cancer is not well defined." (PMID 34301934, 2021).
Duchenne and Becker muscular dystrophies (continued). "Three diseases, namely Neurofibromatosis type 1 (OMIM 162200), Duchenne/Becker muscular dystrophies (OMIM 310200), and Methylmalonic aciduria mut type (OMIM 251000), which were caused by variants in the NF1, DMD, and MUT (MIM 609058) genes, were observed in 14 diagnosed infants (19.44%, 14/72)." (PMID 30968598, 2019). "The Duchenne and Becker muscular dystrophies (DMD, BMD) show significant comorbid diagnosis for autism, and the genomic sequences encoding the proteins responsible for these diseases, the dystrophin and associated proteins, have been proposed as new candidate risk loci for autism." (PMID 26527530, 2015). "Although dystrophin mutations are in general linked to Duchenne/Becker muscular dystrophy (DMD/BMD), no apparent sign of skeletal muscle degeneration were observed in XLDCM patients, which distinguishes them from DMD/BMD patients." (PMID 25340340, 2014). "In addition, our findings support the existence of cardiac-specific functions of dystrophin and may guide studies into early triggers of cardiac disease in Duchenne and Becker muscular dystrophies." (PMID 22937058, 2012). "Several clinical trials are working on drug development for Duchenne and Becker muscular dystrophy (DMD and BMD) treatment, and, since the expected increase in dystrophin is relatively subtle, high-sensitivity quantification methods are necessary." (PMID 37047330, 2023). "The dystrophin (DMD) gene is responsible for the most common inherited muscle diseases, Duchenne and Becker muscular dystrophies (DMD/BMD)." (PMID 21151598, 2010). "The mdx mouse strain, lacking a functional dystrophin gene, has served as the animal model for human Duchenne and Becker muscular dystrophies." (PMID 25999854, 2015).
X-linked disease (37 papers, 2009 to 2026). X-linked form of disease. "It is an X-linked disease chiefly due to a deficiency of dystrophin protein—encoded by DMD gene—with an incidence of 1 in 3500 boys all over the world." (PMID 36834757, 2023). "This X-linked genetic disease is mainly caused by frame-shifting deletions or nonsense mutations in the DMD gene that result in a loss of functional dystrophin protein, leading to fatal progressive muscle wasting." (PMID 28742140, 2017). "Again, it is confirmed that all genetically positive cases were male as DMD is an X-linked disease." (PMID 41179496, 2025). "DMD and BMD are X-linked diseases caused by mutations in the DMD gene, which is responsible for encoding dystrophin protein and is located at locus Xp21." (PMID 22701119, 2012). "DMD and other X-linked genetic diseases do not have the second allele for natural HDR, hence there is no physiologic possibility to restore dystrophin (and X-linked mutations that cause genetic diseases in males, generally speaking) to the wild-type sequence." (PMID 30613384, 2018).